EGFR (epidermal growth factor receptor)
Diseases named in the same sentence as EGFR in open-access papers (continued):
Sharing a sentence is not in itself a finding about the gene and the disease.
non-small cell lung carcinoma (continued). "Tyrosine-kinase inhibitors (TKIs) have become the cornerstone treatment of patients with non-small cell lung cancer that harbor oncogenic EGFR mutations." (PMID 32873256, 2020). "The T790M resistance mutation is present in about one-half of epidermal growth factor receptor (EGFR)-positive advanced non-small cell lung cancer (NSCLC) patients at disease progression." (PMID 33489541, 2020). "For example, EGFR, which is usually mutated within exons 19 and 21 is the gene targeted by Gefitinib in non-small cell lung cancer." (PMID 31927530, 2020). "EGFR mutation status is considered as an important predictor of therapeutic responsiveness in non-small-cell lung carcinoma patients." (PMID 32937815, 2020). "In EGFR-mutated non-small-cell lung cancer patients treated with tyrosine kinase inhibitors, genetic polymorphisms of glutathione S-transferase P1, myeloperoxidase and biliverdin reductase A have been shown to be associated with a reduced overall survival." (PMID 32937815, 2020). "Osimertinib is a third-generation EGFR tyrosine kinase inhibitor that was marketed in 2017 to treat advanced or metastatic non-small-cell lung cancer (NSCLC) carrying a specific mutation." (PMID 33013366, 2020). "Osimertinib is approved by Food and Drug Administration for patients with advanced non-small cell lung cancer carrying EGFR-T790M mutations." (PMID 33203197, 2020). "Oncogenic mutations of epidermal growth factor receptor (EGFR) are responsive to targeted tyrosine kinase inhibitor (TKI) treatment in non-small-cell lung cancer (NSCLC)." (PMID 33396393, 2020). "Epidermal growth factor receptor (EGFR) tyrosine kinase inhibitors (TKIs) are standard first-line treatment for EGFR mutation-driven non-small cell lung cancer (NSCLC)." (PMID 33244458, 2020). "Non-small-cell lung cancer (NSCLC) patients with epidermal growth factor receptor (EGFR) mutation eventually develop resistance to EGFR-targeted tyrosine kinase inhibitors (TKIs)." (PMID 33291316, 2020). "This study determined the frequency and factors associated with EGFR testing rates and erlotinib treatment as well as associated survival outcomes in patients with non small cell lung cancer in Kentucky." (PMID 32810185, 2020). "Epidermal growth factor receptor tyrosine kinase inhibitors (EGFR TKIs) have been first-line therapy in the treatment of non-small cell lung cancer (NSCLC) harboring EGFR sensitive mutations." (PMID 33392095, 2020). "Other cancer that shows EGFR amplification, such as non-small cell lung cancer, shares this ADD3 infraexpression associated with cell migration." (PMID 33172155, 2020). "Around 80 to 85% of lung cancers are non-small cell lung cancers (NSCLCs), and, on average, 33.1% have EGFR mutations, with a higher prevalence in the Asian population." (PMID 33489541, 2020). "EGFR mutations are common in non-small cell lung cancer and patients with these mutations are treated with tyrosine kinase inhibitors." (PMID 33067442, 2020). "Afatinib was also active in non-small cell lung cancer tumors that harbored certain types of uncommon EGFR mutations, especially Gly719Xaa, Leu861Gln, and Ser768Ile, but less active in other mutations types." (PMID 32448366, 2020). "A previous study revealed that EGFR mutations predisposed to the leptomeningeal metastases of EGFR-mutant non-small-cell lung cancer, and the present study further supports this notion." (PMID 32711494, 2020). "The proportion was similar with that for epidermal growth factor receptor mutation in patients with non-small cell lung cancer (12.2%)." (PMID 33150263, 2020). "Targeted therapy is an efficient treatment for patients with epidermal growth factor receptor (EGFR) mutations in non-small cell lung cancer (NSCLC)." (PMID 31936895, 2020). "The National Comprehensive Cancer Network guideline of non-small-cell lung cancer recommended biomarkers favorable for target therapies such as epidermal growth factor receptor (EGFR) mutation." (PMID 33193560, 2020).
non-small cell lung carcinoma (continued). "Src has also been implicated in non-small cell lung cancers harboring mutations in EGFR where Src is activated via Cripto-1." (PMID 32509799, 2020). "EGFR tyrosine kinase inhibitors (TKIs) have demonstrated dramatic efficacy in non-small cell lung cancer (NSCLC) patients with EGFR-activating mutations." (PMID 33014814, 2020). "EGFR inhibitors have been particularly successful in non-small cell lung cancer, an EGFR-driven disease, and they are now the standard of care for patients with an EGFR-sensitizing mutation." (PMID 32552913, 2020). "We have demonstrated that this system can identify a rare single nucleotide variant (EGFR(T790M)) associated with non-small cell lung carcinoma as well as fusion genes (BCR-ABL1 and CCDC88C-FLT3) that are associated with different types of cancer." (PMID 33199817, 2020). "Recent studies indicate the benefit of treatment with osimertinib over that with conventional epidermal growth factor receptor (EGFR) tyrosine kinase inhibitors (TKI) for untreated EGFR-mutated non-small cell lung cancer (NSCLC)." (PMID 32028905, 2020). "Approximately 10% of the epidermal growth factor receptor (EGFR) mutations in non-small-cell lung cancer (NSCLC) are uncommon EGFR mutations." (PMID 33036377, 2020). "It detects epidermal growth factor receptor gene mutations in non-small cell lung cancer patients (10-20% of all lung cancer) (FDA)." (PMID 32774122, 2020). "In non-small cell lung cancer, for example, patients with epidermal growth factor receptor (EGFR) mutation are likely to benefit from tyrosine kinase inhibitors (TKIs)." (PMID 33008377, 2020). "Epidermal growth factor receptor tyrosine kinase inhibitor (EGFR TKI) is beneficial for the treatment of non-small cell lung cancer with EGFR mutation." (PMID 32318350, 2020). "Non-small cell lung cancer (NSCLC) patients with activating EGFR mutations initially respond to first-generation EGFR inhibitors; however, the efficacy of these drugs is limited by acquired resistance driven by the EGFR T790M mutation." (PMID 32404161, 2020). "The somatic activating mutations of EGFR gene are most widely seen in non-small cell lung cancers (NSCLC), especially in the TKD, and are routinely screened in all NSCLC." (PMID 32962681, 2020). "The activating mutations of EGFR occur in approximately ~10% of non-small cell lung cancer (NSCLC) cases in in North America and Western Europe patients and approximately 30–50% in East Asian patients." (PMID 32093124, 2020). "Here, we conducted a meta-analysis to evaluate the association between the persistence of EGFR T790M and the clinical benefits of Osimertinib in non-small cell lung cancer (NSCLC) patients with baseline EGFR T790M mutation." (PMID 32231715, 2020). "Activating mutations in epidermal growth factor receptor (EGFR) drive the strong constitutive expression of tumor PD-L1 in a subset of patients with non-small cell lung cancer." (PMID 32992658, 2020). "Patients with non-small cell lung cancer with an activating EGFR mutation in the tumor, are treated with targeted therapy against this mutation." (PMID 33138052, 2020). "In this review, the authors will focus on the applications of liquid biopsy in EGFR-mutated non small cells lung cancer at diagnosis, during treatment and at progression, describing available data and possible future scenarios." (PMID 36046387, 2020). "Erlotinib is presently the first line treatment for non-small cell lung cancer (NSCLC) with epidermal growth factor receptor (EGFR) active mutation." (PMID 32457635, 2020). "In Taiwan, epidermal growth factor receptor (EGFR) tyrosine kinase inhibitors (EGFR-TKIs), gefitinib, erlotinib, and afatinib are served as first-line therapy for non-small lung cell cancer (NSCLC) patients with EGFR sensitizing mutations." (PMID 33014788, 2020).
non-small cell lung carcinoma (continued). "Early-stage EGFR-mutated non-small-cell lung cancer (NSCLC) cases usually have a better prognosis than wild-type or KRAS-mutated cases, even without tyrosine-kinase inhibitor (TKI) application." (PMID 33247113, 2020). "For example, non-small cell lung cancer (NSCLC) regimens are organized by EGFR, ALK, BRAF, and ROS1 mutation status; kinase inhibitors are categorized by their target kinase(s) and biomarker-specific FDA labeling is noted." (PMID 32117976, 2020). "In non-small-cell lung cancer (NSCLC) activation mutations of EGFR in the tyrosine kinase domain had been identified." (PMID 31936346, 2020). "EGFR mutations were examined to verify the effect of gefitinib on positive non-small cell lung carcinoma in two Phase III clinical trials from Japan." (PMID 32833992, 2020). "One of them was a 26-year-old man with a new diagnosis of acute promyelocytic leukemia and the other one was a 46-year-old man with a new diagnosis of EGFR (Epidermal Growth Factor Receptor) mutated non-small cell lung cancer." (PMID 32974210, 2020). "The major hallmarks and mechanisms of Tumor Immune Escape in the TME of EGFR-mutated non-small cell lung cancer." (PMID 32760402, 2020). "In the present prospective two-cohort phase II trial, 65 patients (T790M cohort, 40 patients; first-line cohort, 25 patients) with radiotherapy-naïve CNS metastasis of EGFR mutation-positive non-small cell lung cancer (NSCLC) will be included." (PMID 32357848, 2020). "Epidermal growth factor receptor tyrosine kinase inhibitors (EGFR-TKIs) greatly improve the survival and quality of life of non-small cell lung cancer (NSCLC) patients with EGFR mutations." (PMID 33363040, 2020). "Epidermal growth factor receptor (EGFR) tyrosine kinase inhibitors (TKIs) have been recommended as the first-line therapy for non-small cell lung cancer (NSCLC) patients harboring EGFR mutations." (PMID 32793190, 2020). "The introduction of tyrosine kinase inhibitors (TKIs) for non-small cell lung cancer (NSCLC) has greatly improved treatment outcomes in patients with epidermal growth factor receptor (EGFR) mutations." (PMID 32224854, 2020). "Investigation of mutations in the second and third generation of EGFR-tyrosine kinase inhibitors in EGFR-mutant non-small cell lung cancer, led to the identification of causative mutation and consequently overcoming targeted resistance." (PMID 32796761, 2020). "Non-small cell lung cancer (NSCLC)-carrying specific epidermal growth factor receptor (EGFR) mutations can be effectively treated by a tyrosine kinase inhibitor such as gefitinib." (PMID 32751169, 2020). "Activating mutations in the epidermal growth factor receptor (EGFR) gene are commonly observed in non-small-cell lung cancer (NSCLC)." (PMID 30854234, 2019). "Comparatively less toxic and more tolerated, epidermal growth factor receptor-tyrosine kinase inhibitors (EGFR-TKIs) are recommendable for advanced non-small-cell lung cancer (NSCLC) patients with EGFR-sensitive mutations." (PMID 30911072, 2019). "Many international guidelines are recommended to detected the EGFR mutation before the treatment of advanced non-small cell lung cancer." (PMID 31315782, 2019). "Another important target for biosensor detection is the “epidermal growth factor receptor” (EGFR); the detection of the mutation of this protein provides valuable information for the detection and the management of non-small cell lung cancer." (PMID 30754727, 2019). "In particular, activating mutations of the EGFR kinase domain, including single amino acid substitutions, insertions and deletions, are commonly observed in non-small cell lung cancer (NSCLC) patients." (PMID 31536605, 2019). "Epidermal growth factor receptor (EGFR) is another effective target for treatment of many epithelial cancers, especially non-small cell lung cancer in which 10–55% patients have EGFR mutation." (PMID 31993373, 2019).
non-small cell lung carcinoma (continued). "Epidermal growth factor receptor (EGFR) is one of the major driving mutations in non-small cell lung cancer (NSCLC)." (PMID 30791921, 2019). "Gefitinib is a first-line targeted therapy for non-small cell lung cancer in patients harboring active mutation of EGFR." (PMID 31514441, 2019). "For example, research revealed that EGFR was amplified and/or mutated in glioma and non-small-cell lung cancer, whereas ErbB2 was amplified in breast, ovarian and bladder cancer and in several other tumors." (PMID 30984788, 2019). "Liquid biopsy is currently approved for management of epidermal growth factor receptor (EGFR)-mutated non-small-cell lung cancer (NSCLC) patients." (PMID 31861832, 2019). "This therapeutic approach in association with Chloroquine acted synergistically to reverse erlotinib resistance in EGFR mutation-positive of non-small-cell-lung cancer (NSCLC)." (PMID 31888119, 2019). "Real world data of efficacy of osimertinib in pretreated patients with advanced non-small cell lung cancer harboring EGFR T790M mutation." (PMID 31442277, 2019). "It is well established that EGFR-targeting TKIs improve the progression-free survival of patients with EGFR-mutated non-small-cell lung cancers (NSCLCs)." (PMID 32089685, 2019). "Here, we examined a common EGFR deletion mutation, Δ746ELREA750, which is frequently observed in non-small cell lung cancer patients." (PMID 31536605, 2019). "Non-small cell lung cancer patients, who harbour cancer cells characterised by activating EGFR mutations, are treated with EGFR tyrosine kinase inhibitors." (PMID 35582596, 2019). "The US FDA approved the first liquid biopsy test on 1 June 2016 for analysis of EGFR mutations in Non-Small Cell Lung Carcinoma (NSCLC) patients using cobas EGFR Mutation Test v2." (PMID 30889786, 2019). "The epidermal growth factor receptor (EGFR)-mutated advanced non-small-cell lung cancer has been successfully treated with tyrosine kinase inhibitors (TKIs)." (PMID 31315676, 2019). "Recent studies have shown that the AXL upregulation underlies epidermal growth factor receptor (EGFR)-tyrosine kinase inhibitor (TKI) resistance in EGFR-mutant non-small cell lung cancer (NSCLC)." (PMID 31497246, 2019). "Uncommon Epidermal Growth Factor Receptor (EGFR) mutations represent a distinct and highly heterogeneous subgroup of Non-Small Cell Lung Cancers (NSCLCs), that accounts for approximately 10% of all EGFR-mutated patients." (PMID 30901844, 2019). "The clinical outcomes of non-small cell lung cancer (NSCLC) patients whose tumors have activated mutations of epidermal growth factor receptor (EGFR) have improved since the introduction of EGFR tyrosine kinase inhibitors (EGFR-TKIs)." (PMID 31380273, 2019). "While ctDNA analysis has been approved for epidermal growth factor receptor (EGFR) mutation detection in metastatic non-small cell lung cancer, it has been suggested as a tool for liquid biopsy in CRC." (PMID 31142037, 2019). "Non-small cell lung cancer (NSCLC) patients with sensitive epidermal growth factor receptor (EGFR) mutations are successfully treated with EGFR tyrosine kinase inhibitors (EGFR-TKIs); however, resistance to treatment inevitably occurs." (PMID 30876460, 2019). "The epidermal growth factor receptor (EGFR) is a member of the ErbB family of tyrosine kinase receptors that is overexpressed or mutated in non-small cell lung cancer and represents the primary target for drugs such erlotinib and gefitinib." (PMID 31970149, 2019). "The mutation status of epidermal growth factor receptor is considered to affect the radiosensitivity of non-small cell lung carcinoma, including the NCI-H1975 cells." (PMID 31800616, 2019).
non-small cell lung carcinoma (continued). "EGFR tyrosine kinase inhibitors are globally established as a first-line treatment for advanced non-small cell lung cancer patients with a sensitizing EGFR mutation." (PMID 31315599, 2019). "The EGFR-mutated advanced non-small-cell lung cancer (NSCLC) has been successfully treated by sequentially administering several tyrosine kinase inhibitors (TKIs)." (PMID 31315676, 2019). "Molecular testing for mutations in the EGFR gene is commonplace for patients with non-small cell lung cancer (NSCLC)." (PMID 30470932, 2019). "Epidermal growth factor receptor (EGFR) mutations are associated with response of tyrosine kinase inhibitors (TKIs) for patients with advanced non-small cell lung cancer (NSCLC)." (PMID 31164704, 2019). "Non-small cell lung cancer cells with KRAS or EGFR mutations and colorectal carcinoma cells also show the dichotomy of AKT1 during tumor progression and metastasis." (PMID 31752925, 2019). "Overexpression or mutation of EGFR plays an important role in the development, differentiation, survival and drug resistance of non-small-cell lung cancer (NSCLC)." (PMID 31261881, 2019). "Diffuse lung metastases have been reported in non-small cell lung cancer (NSCLC) harboring epidermal growth factor receptor (EGFR) mutations." (PMID 31540242, 2019). "Ten patients with EGFR-mutated non-small cell lung cancer underwent dynamic 18F-fluorothymidine PET-CT before, 7 days after, and 28 days after commencing treatment with a tyrosine kinase inhibitor." (PMID 30715647, 2019). "Epidermal growth factor receptor (EGFR) tyrosine kinase inhibitors (TKIs) are given as standard therapy to non-small cell lung cancer (NSCLC) patients who carry activating mutations in the EGFR gene." (PMID 31426531, 2019). "Epidermal growth factor receptor (EGFR) mutation is the most common gene mutation in patients with non-small cell lung cancer (NSCLC)." (PMID 31315782, 2019). "Stat3 inhibitors are currently an important issue, as early clinical data has shown promising results in EGFR mutation- positive non-small cell lung cancer." (PMID 31690341, 2019). "For example, up to 15% of Caucasian patients and 20–40% of Asian patients with non-small cell lung cancer (NSCLC) have an activating EGFR mutation." (PMID 30671765, 2019). "Exosomal nucleic acid (exoNA) is a feasible target to improve the sensitivity of EGFR mutation testing in non-small cell lung cancer patients with limited cell-free DNA (cfDNA) mutant copies." (PMID 31582907, 2019). "Non-small cell lung cancers (NSCLCs) that harbour activating mutations such as exon 19 deletion mutation are particularly sensitive to EGFR-TKIs gefitinib (Iressa) and erlotinib (Tarceva)." (PMID 31523190, 2019). "Mutations on the epidermal growth factor receptor (EGFR) gene were detected in CTCs of non-small-cell lung cancer." (PMID 31650022, 2019). "Inframe insertions of three or more base pairs in exon 20 of the epidermal growth factor receptor (EGFR) gene were among the first EGFR mutations to be identified as oncogenic drivers in non-small cell lung cancer (NSCLC)." (PMID 30854234, 2019). "Non-small cell lung cancer (NSCLC) patients harboring epidermal growth factor receptor (EGFR) mutations often develop brain metastases." (PMID 31655564, 2019). "Osimertinib is a first-line treatment option for patients with metastatic non-small cell lung cancer (NSCLC) harbouring EGFR mutations." (PMID 31921341, 2019). "EGFR inhibitors are now widely used within the clinic as a monotherapy agent for treating patients with non-small cell lung cancer who harbour a specific EGFR mutation." (PMID 31183252, 2019). "Non-small cell lung cancer with EGFR mutations are known to develop resistance to EGFR tyrosine kinase inhibitors." (PMID 31000705, 2019).